BDNF (brain derived neurotrophic factor)
Diseases named in the same sentence as BDNF in open-access papers (continued):
Sharing a sentence is not in itself a finding about the gene and the disease.
retinopathy (15 papers, 2018 to 2025). "Variants in brain-derived neurotrophic factor (BDNF) have been connected with the grade of retinopathy of prematurity." (PMID 40002629, 2025). "Localizing the BDNF is intriguing because it has been demonstrated that its decrease is associated with age-dependent macular degeneration and retinopathy." (PMID 38473977, 2024). "The BDNF/TrkB pathway in learning and memory, chronic pain, and retinopathy has been deeply studied, but there are few studies on neuronal apoptosis." (PMID 35338452, 2022). "In this regard, the neuroprotective brain-derived neurotrophic factor (BDNF) has recently emerged as a potential target in retinal disorder pathogenesis, due to its beneficial effects on retinal neuronal layers." (PMID 36077579, 2022). "Why is it important to reveal the role of BDNF in neuroprotection in DR and hypoxic retinal disorders?" (PMID 34068807, 2021). "We concluded that there is a significant decline in serum BDNF levels in type 2 diabetics with established retinopathy when compared with the healthy control group." (PMID 33457130, 2020). "In light of this increasing burden among our population, we planned the current study to determine the levels of BDNF and glycated hemoglobin (HbA1c) with the progression of retinopathy in the present study." (PMID 33457130, 2020). "The BDNF protein content of Muller cells in OXYS rats can also point to obstructed BDNF transport in the optic nerve during the development of retinopathy." (PMID 30871541, 2019). "Clinically, preterm infants who experienced proliferative retinopathy had decreased serum levels of BDNF compared to full-term." (PMID 30131506, 2018). "Optimal doses of the brain-derived neurotrophic factor at the early stages of retinopathy may have a neuroprotective effect." (PMID 32509339, 2020). "Previous studies have highlighted BDNF as a significant factor in the progress of retinopathy." (PMID 33457130, 2020). "Indeed, in healthy rats mature BDNF (mBDNF) immunoreactivity was detected in the ganglion cells and in the Muller cells, while only the Muller cells displayed mBDNF protein in rats affected by retinopathy." (PMID 35269763, 2022). "The results from this study provide evidence for changes in the expressions of BDNF, CNTF, and FGF-2 in Oxygen-induced retinopathy." (PMID 36532277, 2022). "In contrast, we observed only subtle changes in the labeling of mature BDNF (mBDNF) and TrkB during the development of AMD-like retinopathy in OXYS rats." (PMID 30871541, 2019). "This study provides evidence for changes in BDNF, CNTF, and FGF-2 in Oxygen-induced retinopathy." (PMID 36532277, 2022). "On analysis, a significant decline was seen in serum BDNF levels in diabetics as compared with non-diabetics (p < 0.001), but a significant reduction in levels with the progression of retinopathy was observed (p < 0.001)." (PMID 33457130, 2020). "In the present study, a comparison between the serum levels of BDNF and HbA1c among diabetics with or without retinopathy was done taking non-diabetics as the healthy group." (PMID 33457130, 2020). "Serum BDNF levels were also compared among diabetics on the basis of the presence or absence of retinopathy." (PMID 33457130, 2020).
heart diseases (14 papers, 2010 to 2025). "The loss of BDNF and its receptor, tropomyosin receptor kinase B, in signaling pathways is also associated with increased susceptibility to brain and heart diseases." (PMID 39648800, 2024). "Our results further support the association between BDNF levels and cardiac disease." (PMID 20404913, 2010). "Hence, an association between low levels of BDNF in the serum and an increase in cardiovascular risk, severe cardiac diseases, coronary heart disease (CHD), and the growth factor is seen, which directs the response of the cardiovascular system to acute and chronic injury." (PMID 36742047, 2022). "Several studies reported a protective role of BDNF in neurodegenerative disorders, cardiac diseases, and also a potential role in recovery post-injury." (PMID 40427122, 2025). "The plasma exosomes of gut origin can be taken up by cardiomyocytes where they release the cargo causing molecular remodeling by dysregulating critical signaling molecules like BDNF, leading to heart diseases eventually." (PMID 35274002, 2022). "RAD21, the third most significant gene, is related to memory formation (through genomic structure of BDNF and Arc) as well as to heart diseases." (PMID 29322921, 2017). "Lately, studies found that BDNF was relevant to exercise in heart diseases." (PMID 33477900, 2021). "Taken together, circulating BDNF may be a candidate biomarker for some cardiac diseases." (PMID 33477900, 2021). "Mutations in BDNF might also cause congenital central hypoventilation syndrome, characterized by hypoventilation due to the absence of primary neuromuscular, lung, or cardiac disease, or an identifiable brainstem lesion." (PMID 29691431, 2018).
cerebral artery (13 papers, 2014 to 2025). "A hyaluronan/methylcellulose hydrogel modified with the anti-inflammatory peptide KAFAKLAARLYRKALARQLGVAA (KAFAK) and brain-derived neurotrophic factor (BDNF) was developed for spinal cord injury (SCI) regeneration." (PMID 39063768, 2024).
inflammation (12 papers, 2006 to 2026). Aberrant reaction of the microcirculation characterized by movement of fluid and leukocytes from the blood into extravascular tissues. "Results showed that BDNF neutralizing antibody partially reversed the decreases in micturition intervals caused by colonic inflammation." (PMID 22335898, 2012). "Previous studies identified the changes in a number of nociception-related genes, such as calcitonin gene-related peptide (CGRP), substance P (SP), and brain-derived neurotropic factor (BDNF) in the pelvic organs after transient colonic inflammation." (PMID 30687029, 2018). "Brain inflammation, oxidative injury, and BDNF levels are consistently altered in septic animals, as well as in the plasma of septic patients that develop brain dysfunction." (PMID 27229490, 2017). "The role of BDNF in bladder inflammation was evaluated by intrathecal injections of either a general Trk receptor antagonist or a BDNF scavenger." (PMID 24788240, 2014). "The level of BDNF high affinity receptor TrkB is increased in bladder afferent neurons during colonic inflammation." (PMID 22335898, 2012). "Preclinical mice studies suggest that intermittent fasting may improve cognitive function by increasing the production of brain-derived neurotrophic factor (BDNF), a protein involved in the growth and survival of neurons, reduction of brain inflammation, and promotion of autophagy." (PMID 39790469, 2024). "Taken together, gut inflammation and prolonged psychological stress could affect microglia numbers and BDNF- CREB signaling, resulting in pain and negative affect." (PMID 30356873, 2018).
movement disorder (12 papers, 2012 to 2025). Neurological conditions resulting in abnormal voluntary or involuntary movement, which may impact the speed, fluency, quality and ease of movement. "Reduced BDNF expression in HT zebrafish results in alterations in the brain proteome, leading to an increase in movement disorder categories." (PMID 37958719, 2023). "In a population with chronic mental illness, various SNPs in 10 candidate genes (PPP1R1B, BDNF, DRD3, DRD2, HTR2A, HTR2C, COMT, MnSOD, CYP1A2, and RGS2) reached nominally significant (p≤0.05) associations with drug-induced movement disorder." (PMID 22615781, 2012).
adenocarcinoma (7 papers, 2011 to 2020). A common cancer characterized by the presence of malignant glandular cells. "The brain-derived neurotrophic factor (BDNF)/tyrosine receptor kinase B (TrkB) pathway was previously associated with key oncogenic outcomes in a number of adenocarcinomas." (PMID 33255325, 2020). "The BDNF/TrkB pathway activates downstream pathways such as PI3K/Akt, and is associated with key oncogenic outcomes in a variety of adenocarcinomas, including lung, breast, gastric, colorectal and salivary gland adenoid cystic carcinoma." (PMID 33255325, 2020). "We then treated NSCLC cell lines (HCC95=SCC, Calu 6=adenocarcinoma, H1703= adenosquamous) with BDNF alone or in the presence of the TrkB inhibitor AZD7451 and compared phopho-TrkB levels." (PMID 29581842, 2018). "Expression of this receptor in A549 cells and in another adenocarcinoma cell line, NCI-H441, promoted enhanced migratory capacity in wound healing assays in the presence of the TrkB ligand BDNF." (PMID 24959744, 2014). "BDNF and receptor expression was evaluated by RT-PCR in CRC samples obtained surgically from 16 patients with adenocarcinoma." (PMID 21966426, 2011).
immune disease (5 papers, 2018 to 2025). "Genetic and epigenetic studies reveal how BDNF, SLC6A4, and immune disease-associated gene variants predispose to both conditions, with early trauma causing enduring molecular damage by DNA methylation." (PMID 40941042, 2025). "Overall, proBDNF and BDNF levels are increased and decreased, respectively, in MS due to immune disorders and inflammatory responses." (PMID 39654365, 2024).
bacterial infection (4 papers, 2021 to 2024). "Bacterial infection affects memory consolidation in older rats, reduces levels of BDNF in the hippocampus and decreases activated TrkB in the hippocampus, which is rescued by IL-1R antagonists." (PMID 38263132, 2024). "Following bacterial infection, BDNF pretreatment reduces the expression of TNF-α, IL-16, IL-1β, and the NFκB pathways, and increases IL-10 and Trk expression." (PMID 34831151, 2021). "BDNF is well-established as a key factor in neuronal development and plasticity and has been shown to reduce inflammation and neuronal apoptosis in response to bacterial infections." (PMID 38879567, 2024).
respiratory disease (4 papers, 2010 to 2025). "The expression and regulation of BDNF in ASM, along with its roles in ASM function and pathological processes, highlight the potential importance of BDNF in respiratory diseases." (PMID 40034284, 2025).
CNS tumors (3 papers, 2021 to 2026). "And, a common polymorphism in BDNF, Val66Met, shows valine homozygosity associates with higher IQs, processing speed, and memory in adults, but lacks demonstrated impact on neurocognitive function in adult CNS tumor survivors." (PMID 35814456, 2022).
benign tumor (2 papers, 2022 to 2024). "The levels of CA19-9, CA125, NLR, PLR, and BDNF in the advanced group were higher than those in the mid-stage and benign tumor group." (PMID 36120557, 2022). "During pregnancy, due to surge of Brain-derived neurotrophic factor (BDNF), CNS benign tumors may mimic malignancy due to increased proliferation rate." (PMID 38993517, 2024).
gastrointestinal disorders (2 papers, 2019 to 2024). "Supporting this claim, animal and human studies showed that BDNF signalling is reduced in the gut and correlated with gastrointestinal disorders in PD by inducing gut inflammation and dysregulation of gut microbiota." (PMID 38752280, 2024). "The results were similar to the patients with functional gastrointestinal disorders, whose BDNF expression in intestine increased significantly and had close relation to the increase of its intestinal tract sensitivity." (PMID 31871476, 2019).
hematological disease (2 papers, 2023 to 2025). "By the date of the publication, it is the first work that evaluates the protein balance between pro-BDNF/BDNF in a hematological disease context." (PMID 40427122, 2025). "Of note, the detected miR15a inhibitory action on BDNF is based on studies conducted on hepatocellular and hematological malignancies." (PMID 36614208, 2023).
infectious disease (2 papers, 2022 to 2025). A disorder directly resulting from the presence and activity of a microbial, viral, or parasitic agent in humans. "Our findings expand these insights to infectious diseases, demonstrating that BDNF can regulate ferroptosis-related gene expression, thereby enhancing host defense mechanisms against Mtb." (PMID 40738187, 2025). "Although we controlled for prenatal malformations, known genetic conditions at birth and infectious diseases, one of the variables that has been observed to modulate BDNF expression is maternal obesity and we lacked this data." (PMID 35208502, 2022).
inflammatory myopathy (2 papers, 2021 to 2024). "The serum BDNF levels may be a useful surrogate biomarker of increased CV risk, the HF-related myopathy, and adverse prognosis in patients having HF." (PMID 33520013, 2021). "Moreover, in animal model of HF and among patients with HFrEF, low levels of BDNF were associated with reduced physical activity and a risk of HF-related myopathy." (PMID 33520013, 2021). "Irisin, BDNF, FGF-21, and probably osteonectin are the most promising biomarkers of HF-related myopathy and cachexia, while their role in the prediction of adverse cardiac remodeling and poor outcomes requires to be elucidated in the future." (PMID 33520013, 2021).
neoplasms of the nervous system (2 papers, 2023 to 2025). "First, BDNF, WDPCP, APC and SMO are associated with neoplasms of the nervous system, especially the pituitary gland (group BN)." (PMID 40831500, 2025).
animal disease (1 paper, 2023). "The highly-potent action of LSD at the BDNF TrkB receptor has recently been highlighted in pre-clinical work, with other work showing potent anti-inflammatory effects of psychedelics in animal disease models, and effects on gene expression." (PMID 37759038, 2023).
cutaneous disorders (1 paper, 2022). "Unfortunately, we were unable to find studies related to the expression of BDNF rs11030094 polymorphism in skin disorders." (PMID 35905107, 2022). "The data on the contribution of BDNF levels to pathophysiology of different cutaneous disorders remain controversial." (PMID 35905107, 2022). "Therefore, the potential significance of BDNF SNPs in the pathogenesis of skin disorders is in the process of investigation." (PMID 35905107, 2022). "There is no data on associations of SNPs with serum levels of BDNF in patients with the skin disorders." (PMID 35905107, 2022).
genetic disease (1 paper, 2011). "However, if the disease of interest is a rare genetic disease and only small cohorts of patients are available, small variations in the protocols used for different blood banks may introduce issues related to plasma sample preparation that affect BDNF measure." (PMID 21857974, 2011).
urological diseases (1 paper, 2012). "The circulating inflammatory biomarkers such as NGF or BDNF might be the underlying pathophysiology of mixed urological disorders and non-urological diseases." (PMID 23028581, 2012).
BDNF also shares sentences with these, for which no sentence is quoted: alcoholism (31 papers); frontotemporal dementia (11); generalized anxiety disorder (10); Hypoglycemia (10); acute myocardial infarction (9); unstable angina (8); allergies (6); hemorrhage (6); knee osteoarthritis (6); subarachnoid hemorrhage (6); Lewy body dementia (5); oral squamous cell carcinoma (5); pancreatic adenocarcinoma (5); Cerebellar Ataxia (4); chronic fatigue syndrome (4); concussion (4); hypertriglyceridemia (4); Sleep disturbance (4); Wilms tumor (4); aniridia (3); Arrhythmia (3); choriocarcinoma (3); endocrine disorders (3); Hearing impairment (3); hepatitis C (3); Hypercholesterolemia (3); idiopathic pulmonary fibrosis (3); influenza (3); pneumonia (3); Prader-Willi syndrome (3).
A further 224 diseases each share a sentence with BDNF in 3 papers or fewer.